CD163 (CD163 molecule)
Diseases named in the same sentence as CD163 in open-access papers (continued):
Sharing a sentence is not in itself a finding about the gene and the disease.
breast carcinoma (continued). "In this regard, Shabo & Svanvik reported that 48% of breast cancer cells expressed CD163, and that 31% of rectal cancer cells expressed it." (PMID 26267609, 2015). "Our study was in accordance with the researches in bladder and breast cancer, suggesting that CD68 and CD163 are important diagnostic and prognostic factors in OSCC." (PMID 24883329, 2014). "Results of immunocytochemical analysis revealed that macrophages incubated with normoxic breast cancer cells CM expressed CD206/CD163 minimally." (PMID 25051364, 2014). "The extent of infiltrating CD163+ or CD68+ myeloid cells in tumor nest versus tumor stroma was evaluated by immunohistochemistry in tissue microarrays with tumors from 144 breast cancer cases." (PMID 22824040, 2012). "In line with previous papers reporting that the content of TAMs inversely correlates with ER expression in breast cancer, CD163+ macrophages located in TS correlated with ER negativity." (PMID 22824040, 2012). "CD163+ cells were in particular abundant in triple-negative/basal-like breast cancer, which was a small patient group in our TMA." (PMID 22824040, 2012). "Breast cancer tumors with dense infiltration of CD163+ macrophages in the TS were of higher grade (P<.001), larger size (P<.001) and had a higher proliferation index as indicated by Ki67 positivity (P = .007)." (PMID 22824040, 2012). "Immunohistochemistry was used to examine the expression of the M2-specific antigen CD163 in paraffin-embedded mammary carcinoma blocks to explore fusion events in breast cancer patients." (PMID 22848668, 2012). "We found that the CD163 expression rate in breast cancer tissues varied significantly and correlated with estrogen receptor status (p<0.05)." (PMID 22848668, 2012). "Eighty percent of the triple-negative/basal-like breast cancer patient had dense infiltration of CD163+ macrophages in TS, while 23% had dense infiltration of CD68+ macrophages in TS." (PMID 22824040, 2012). "In line with the findings from the TMA-based analysis, basal-like breast cancer had significantly higher gene expression levels of CD163 (P<.001) compared to luminal breast cancer, but also of CD68 (P<.05) (data not shown)." (PMID 22824040, 2012). "We can exclude that the majority of the CD163+ cells are MDCs since the CD208+ mature MDCs in this breast cancer cohort were only located in the peri-tumoral T cell rich areas." (PMID 22824040, 2012). "Triple-negative/basal-like and luminal A breast cancers had different recruitment or differentiation patterns of CD163+ and CD68+ macrophages in TS." (PMID 22824040, 2012). "For example, two hub genes of modules, PDGFRL and CD163, also show very weak expression similarities across all seven breast cancer datasets: the average Pearson correlation between these two genes is only 0.24." (PMID 18366601, 2008). "Breast carcinoma tissue was analyzed by Cobas PIK3CA mutation test for the presence of PIK3CA mutation and immunohistochemistry was applied to assess PD-L1 expression and CD4, CD8, CD68, and CD163 infiltration within tumor." (PMID 41096755, 2025). "CD163+ anti-inflammatory myeloid cells, including tumor associated macrophages (TAMs), are known to be of relevance in early breast cancer but their role in MBC is not yet established." (PMID 39751847, 2025). "It was observed that the expression of CD163+ in the tumor stroma was associated with the absence of hormone receptors and an increase in the aggressive characteristics of this type of breast cancer." (PMID 38791312, 2024). "As CD8 + T cells and myeloid cells make a large part of inflammatory infiltrate in TME, in this study we assessed the state of CD8 + T cells along with CD163 + macrophages and PD-L1 status in a well-characterized cohort of 791 treatment-naïve breast cancer patients." (PMID 38349444, 2024).
breast carcinoma (continued). "We investigated CD163+ macrophages in relation to clinicopathologic variables and breast cancer outcomes in the Women’s Circle of Health Study and Women’s Circle of Health Follow-up Study populations of predominantly Black women with breast cancer." (PMID 38720366, 2024). "Interestingly, CD163+ TAMs were positively correlated with breast tumor size, corroborating the pro-tumor function of CD163+ macrophages in breast cancer." (PMID 39513934, 2024). "Furthermore, we have also underscored the significance of the spatial distribution of CD163 TAMs and their interactions with TILs in breast cancer prognosis." (PMID 38893266, 2024). "Besides, this is the first study showing that proliferating CD8 + /TCF1 + T cells and CD163 + /PD-L1 + macrophages are independent prognostic markers for DFS in patients with breast carcinoma." (PMID 38349444, 2024). "Univariate analyses showed that CD163+ cell densities differed between Black and White women, but these differences were attenuated in the multivariable analyses that adjusted for age, grade, tumor size, and breast cancer subtype." (PMID 38720366, 2024). "Slit2 also increases the expression of matrix metalloproteinases in M1-TAMs, which attenuates fibrosis in a mouse model of breast cancer.High expression of Slit2 correlates with improved survival and is negatively correlated with the density of CD163 + TAMs in patient samples." (PMID 39068459, 2024). "(B) Spearman correlation analysis between breast cancer tumor size and CD163 +TAM staining." (PMID 39513934, 2024). "Furthermore, single-cell profiling of myeloid cells from patients with breast cancer identified lipid-associated macrophages that co-expressed the TTR macrophage markers CD63, LIPA, GPNMB, MCR1, CD163, and MSR1." (PMID 38942020, 2024). "Moreover, univariate COX analysis showed that the factors including tumor stage, N stage, CD163 expression, CXCL1 expression, HMGB1 expression, and IGF1R expression were significantly associated with breast cancer prognosis." (PMID 39394189, 2024). "Considering that the numbers of CD163+ TAMs were similar in HER2+ and HER2− tumors, the pro-tumoral functions of CD163+ TAMs can be hypothesized to be especially crucial for the progression of HER2+ breast cancer." (PMID 38339385, 2024). "In addition, decreased TGF-β in breast cancer CM resulted in suppressed CD163 mRNA expression in THP-1-derived macrophages." (PMID 36980788, 2023). "Previous studies have demonstrated that CD163+ macrophages in the tumour stroma of breast cancer tissues correlated to high tumour grade, larger tumour size, triple negative cancers, and suggest that CD68+ macrophages in the tumour stroma is an independent prognostic marker for cancer free survival." (PMID 37108548, 2023). "Although CD163+ MØs, CCL2 and CCL7 are associated with cancer metastasis and poor prognosis and high CCL2 levels are found in various cancer types, including breast cancer and some NSCLC31–33, blocking the CCL2/CCR2 axis alone does not impede tumors from recruiting monocyte-origin resident MØs5." (PMID 38076998, 2023). "Furthermore, CD163+macrophages were found to be located around adipocytes in breast cancer tissues, and their recruitment and polarization were mediated by the upregulated expression of CCL2 and CCL5 in the TAME." (PMID 37454080, 2023). "In addition to the well‐known effects on growth hormone and prolactin gene transcription, it has been demonstrated that CD163+ macrophages induce POU1F1 expression in breast cancer cells." (PMID 36373483, 2023). "However, there was a similar number of CD163+ macrophages in mammary tumours of the 2‐ME‐treated and control groups." (PMID 37649158, 2023). "Primary TNBC tissues express high levels of CD163+ M2-like macrophages, and the expression of CD163+ in the tumor stroma is associated with the absence of hormone receptors and increased aggressive features of breast cancer." (PMID 35960749, 2022).
breast carcinoma (continued). "We found that high expression of CD163 was detected in 43/105 (40.9%) breast cancer tissues, and high CD163 expression was found to be significantly correlated with lymph node metastasis (p = 0.012), but not with other clinicopathological parameters, such as age and TNM stage." (PMID 35715860, 2022). "Moreover, cPLA2 gene expression is also significantly positively correlated with CD163+ M2-TAMs in breast cancer patients." (PMID 35135586, 2022). "Higher expression of CD163 was observed in metastatic breast cancer compared to primary breast cancer, indicating that it may change during tumor progression." (PMID 36551651, 2022). "A higher density of CD163+ TAM cells and a shorter distance could be regarded as a clinical and pathological risk factor for breast cancer." (PMID 36551651, 2022). "Finally, to evaluate the clinical significance of our findings, we performed immunohistochemistry (IHC) staining of breast cancer tissue microarray slides (TMAs) using anti-CD163 (TAM marker), anti-ZEB1 and anti-DNMT1 antibodies." (PMID 36273188, 2022). "Moreover, high expression of CD163+ TAMs was related to poor prognosis in breast cancer, gastroesophageal adenocarcinoma, HCC, human sarcoma, but not in melanoma patients." (PMID 36686729, 2022). "We acknowledge that the predictive impact of CD163+macrophages was obtained by their measurement within pre-treatment biopsy samples, as performed in previous studies of neoadjuvant chemotherapy for esophageal and breast cancer." (PMID 35658848, 2022). "Moreover, we provide data to show poor clinical outcomes in breast cancer patients with exceedingly high CD8+ TC/IM ratios, which were associated with increased frequencies of CD163+ and FoxP3+ cells." (PMID 36551693, 2022). "More importantly, we found that CD163 was differentially expressed in several types of breast cancer tissues, with a significantly higher proportion in triple-negative breast cancer tissues than in luminal and Her2-positive breast cancer tissues." (PMID 35715860, 2022). "We next examined whether ADAM17 directly regulates the number of CD163+ cells, using orthotopic mouse mammary tumors." (PMID 35998057, 2022). "Furthermore, we also determined the prognostic significance of CSF-1R+ tumor-associated macrophages and their association with lymphocytic infiltrates expressing immune checkpoint and CD163+ M2 macrophage biomarkers in the context of ER+ breast cancers." (PMID 34830923, 2021). "Then, we questioned whether NAC affects the accumulation of CD163-positive monocytes into breast cancer tissue." (PMID 35237501, 2021). "Moreover, tumor hybrids were positive for the expression of the macrophage marker CD163, which has also been found in human breast cancer specimens, suggesting that such cells were originated through cell-cell fusion." (PMID 34207991, 2021). "As well, the expression of CD163 was demonstrated in breast cancer cells and in malignant melanoma." (PMID 33466316, 2021). "Additionally, TEMs also show a unique surface marker profile consisting of Tlr4, Mrc1, Il4ra, and CD163, which differentiate them from TAMs in murine mammary tumors." (PMID 33968034, 2021). "Only CD163, not M2-signature, showed an association with poor prognosis in breast cancer (p-value = 0.021)." (PMID 33277616, 2020). "Interestingly, we saw the most substantial predictive impact of DEK and CD163 staining in luminal breast cancers." (PMID 32708944, 2020). "Although they are less well-studied, CD20+ B cells, which play an integral role in humoral immunity and shape the functions of other immune cells, and CD163+ cells, a marker of anti-inflammatory M2 macrophages, may also have prognostic value in breast cancer." (PMID 32698885, 2020). "To explore whether the correlation between MCT1 and CD163 also existed in additional breast cancer cases, we downloaded breast cancer expression files from The Cancer Genome Atlas (TCGA) database." (PMID 33178603, 2020).
breast carcinoma (continued). "Moreover, using an indirect trans-well system in which THP-1 was co-cultured with various breast cancer cell lines that mimicked the tumor microenvironment, we observed an increase in CD163 in the MDA-MB-231 group." (PMID 33256011, 2020). "Specific role of CD204 was found in the Japanese cohort, where high number of CD204+ but not CD68+ or CD163+TAMs was associated with worse relapse-free survival and breast cancer-specific survival." (PMID 33194645, 2020). "Another study showed that CD163+ macrophages in tumor stroma were positively correlated with certain pathologic characteristics seen in MBCs, such as higher grade, larger tumor size, and triple-negative/basal-like breast cancer." (PMID 31937323, 2020). "On comparing the number of immune cells expressing immune cell subtype-related proteins, we found that the expression of STAT6 (p = 0.005), FOXP3 (p = 0.001), CD8 (p = 0.012), CD68 (p = 0.011), and CD163 (p < 0.001) differed significantly according to the breast cancer molecular subtypes." (PMID 32580398, 2020). "Also, for different types of breast cancer, there is a difference in prognostic value of the number of CD163+ cells in tumor stroma." (PMID 32884895, 2020). "Therefore, we compared the infiltration level of CD163+ macrophages in different breast cancer subtypes." (PMID 33178603, 2020). "In Swedish, Norway, Chinese, and Egyptian cohorts of patients, CD163+ macrophages positively correlated with estrogen and progesterone receptor negativity, triple-negative/basal-like breast cancer and inversely correlated with luminal A breast cancer." (PMID 33194645, 2020). "Increased infiltration of MCT1+CD163+ macrophages in the margin, rather than in the malignant tissues, was associated with poor prognosis for breast cancer patients and was an independent risk factor for predicting rapid progression of breast cancer." (PMID 33178603, 2020). "Interestingly, we found that breast cancer cells induced high CD163 and CD206 expressions on monocytes as well as MHC class II (HLA-DR) expression; whereas CAFs did not induce HLA-DR expression on monocytes." (PMID 30816272, 2019). "Apart from the mouse model, it was further explored whether PD-L1 expression correlated to a pro-tumoral “M2”-like (CD163+) TAM phenotype or an anti-tumoral CD11c+ macrophage/dendritic cell phenotype in breast cancer patient samples." (PMID 31581535, 2019). "CD163 expression (of any proportion) in breast cancer cells was found in 43 patients (53%)." (PMID 30915533, 2019). "Most immune cells surrounded the mammary tumors, including CD163+ TAMs." (PMID 31921184, 2019). "Our findings, identified ER+ tumors with high levels of MMP-9/CD163 co-expression as the potential target breast cancer group that could benefit from an MMP-9 targeting modality." (PMID 30558648, 2018). "CD163-expression in breast cancer cells was found in 19 (23%) of the patients." (PMID 29725763, 2018). "The significant association between CD163+ TIMs in primary breast cancers and metastatic ALNs and pCRs with NAC has not been previously reported." (PMID 28913366, 2017). "To investigate whether myeloid cells can promote stroma formation in TN tumours, or if the stroma of TN tumours secretes factors that attract CD163+ myeloid cells, we first generated breast cancer xenograft models." (PMID 27725631, 2016). "To that end, we co-xenotransplanted primary human monocytes (Mo; the proposed precursors of CD163+ myeloid cells) from healthy blood donors together with human breast cancer cells of the luminal A (MCF-7 or T47D cells) or TN (MDA-MB-231 or SUM-159 cells) subtypes in highly immunodeficient NSG-mice." (PMID 27725631, 2016). "In order to determine the role of COX-2 in breast TAMs, a double immunofluorescent staining of COX-2 and CD163 (a specific marker for TAMs) was performed in a breast tissue array containing 160 human breast cancer tissue specimens and 10 pericarcinoma tissue controls." (PMID 26359357, 2015).
breast carcinoma (continued). "However, in one report the density of CD163+ TAMs in the tumor stroma was positively correlated with triple-negative/basal-like breast cancer and inversely correlated with luminal A breast cancer." (PMID 25776849, 2015). "Furthermore, CD163+ macrophages in TS correlated with triple-negative/basal-like breast cancer and inversely with luminal A breast cancer." (PMID 22824040, 2012). "While the presence of CD163+ macrophages in TS was more strongly associated with less favorable clinicopathological features, CD68+ macrophages in TS was a significant independent risk factor for a reduced breast cancer specific survival." (PMID 22824040, 2012). "The mean positive rate of CD163, which has been reported to be a relatively specific marker of M2 macrophages, was 21% (ranging from 1% to 93%) and 35% (ranging from 2% to almost 92%) among breast cancer cells in ER+++ and ER- cases, respectively (p<0.05)." (PMID 22848668, 2012). "Luminal A breast cancer patients with dense infiltration of CD163+ macrophages had a worse OS." (PMID 22824040, 2012). "Since CD163+ macrophages in the TS positively correlated with triple-negative/basal-like breast cancer and inversely correlated with luminal A breast cancer, the prognostic value of CD163+ macrophages in TS was evaluated separately in the two different breast cancer subtypes." (PMID 22824040, 2012). "Further examination of NAMPT expression in breast cancer tissues through TIMER, TISIDB, and HPA databases demonstrated a positive association between NAMPT levels and macrophage immune enrichment, as well as a correlation with the M2 macrophage markers CD163 and CD206." (PMID 40083697, 2025). "A recent study that investigated multiple macrophage markers in relation to breast cancer outcomes showed that when examining the ER-positive versus ER-negative groups separately, high expression of CD163 was associated with improved OS in ER− cases, but not in ER+ cancers." (PMID 38720366, 2024). "In addition, CD163 mRNA expression in THP-1-derived macrophages treated with CM from breast cancer cells was significantly downregulated when HSP70 was diminished by siRNAs in breast cancer cells." (PMID 36980788, 2023). "Our results demonstrate that close spatial proximity of CD163+ TAMs to cancer cells and the average number of CD163+ cells either directly adjacent to or within communicating distance of each cancer cell are independent predictors of unfavorable prognosis in breast cancer." (PMID 35053472, 2022). "In this set of patients, high CD163+ infiltration was strongly associated with unfavorable prognosis factors, such as proliferation, poor tumor differentiation, and ER negativity, supporting the importance of TAM polarization into M1 and M2 phenotypes in breast cancer disease." (PMID 36551522, 2022). "In a cohort of 40 HER2+ breast cancer patients who received trastuzumab, an anti-HER2 therapy, a high number of M1-like macrophages (iNOS+) were significantly associated with improved survival whereas high expression of M2-like macrophages (CD163+) were associated with worse prognosis." (PMID 33968034, 2021). "Former studies of Shabo and colleagues already demonstrated that breast cancer expression of CD163 was correlated to early distant recurrence and reduced patient survival, which further indicates that tumor hybrid cells could be more malignant than parental type tumor cells." (PMID 34207991, 2021). "Notably, more than 50% CD163-positive breast cancer cells were found in about 26% of the biopsies." (PMID 34207991, 2021). "Moreover, a high density of CD163+ TAMs in both TS and TN were correlated with higher histological grade (p < 0.001; p = 0.010), higher recurrence rate (p < 0.001; p = 0.004), and higher breast cancer mortality (p = 0.004, p = 0.012)." (PMID 32607685, 2020). "Therefore, for luminal subtypes, the high expression of DEK may promote a unique CD163+ subset of luminal breast cancers, which will need to be evaluated in future studies." (PMID 32708944, 2020).